EMD (emerin)
Description:
Stabilizes and promotes the formation of a nuclear actin cortical network. Stimulates actin polymerization in vitro by binding and stabilizing the pointed end of growing filaments. Inhibits beta-catenin activity by preventing its accumulation in the nucleus. Acts by influencing the nuclear accumulation of beta-catenin through a CRM1-dependent export pathway. Links centrosomes to the nuclear envelope via a microtubule association. Required for proper localization of non-farnesylated prelamin-A/C. Together with NEMP1, contributes to nuclear envelope stiffness in germ cells. EMD and BAF are cooperative cofactors of HIV-1 infection. Association of EMD with the viral DNA requires the presence of BAF and viral integrase. The association of viral DNA with chromatin requires the presence of BAF and EMD.
Synonyms: EDMD; STA; LEMD5; CMD3C
Tractability: Antibody: UniProt predicts a signal peptide or a membrane-spanning region. PROTAC: ubiquitination databases record sites on it; its protein half-life has been measured.
Gene: Protein-coding gene on chromosome X (154,379,244 to 154,381,574, forward strand). Ensembl gene ENSG00000102119.
Subcellular location: Nucleus inner membrane; Nucleus outer membrane
Subcellular location (Human Protein Atlas): Nuclear membrane; Endoplasmic reticulum
Pathways (Reactome):
Signal Transduction: RAC1 GTPase cycle; RAC2 GTPase cycle; RAC3 GTPase cycle; RHOD GTPase cycle; RHOG GTPase cycle
Cell Cycle: Depolymerization of the Nuclear Lamina; Initiation of Nuclear Envelope (NE) Reformation; Nuclear Envelope Breakdown
Protein localization: Insertion of tail-anchored proteins into the endoplasmic reticulum membrane
Gene Ontology:
Molecular function: actin binding; beta-tubulin binding; cadherin binding; protein binding
Biological process: amyloid fibril formation; cellular response to growth factor stimulus; negative regulation of canonical Wnt signaling pathway; negative regulation of fibroblast proliferation; nuclear membrane organization; positive regulation of protein export from nucleus; regulation of canonical Wnt signaling pathway; muscle contraction; muscle organ development
Cellular component: cortical endoplasmic reticulum; cytoplasm; endoplasmic reticulum; membrane; nuclear envelope; nuclear inner membrane; nuclear membrane; nuclear outer membrane; nucleoplasm; spindle pole centrosome; cytosol; spindle; nucleus; TMEM240-body
Homologues: Orthologues: chimpanzee EMD (99% identical), macaque EMD (93% identical), pig EMD (77% identical), mouse Emd (76% identical), rabbit EMD (76% identical), rat Emd (73% identical), dog EMD (70% identical), guinea pig EMD (65% identical), tropical clawed frog emd (26% identical).
Diseases named in the same sentence as EMD in open-access papers:
EMD is named in the same sentence as 83 diseases in open-access papers, as found by Europe PMC text mining. Sharing a sentence is not in itself a finding about the gene and the disease. The quoted sentences say what the papers report.
Emery-Dreifuss muscular dystrophy (61 papers, 2004 to 2026). Emery-Dreifuss muscular dystrophy (EDMD) is characterized by muscular weakness and atrophy, with early joint contractures and cardiomyopathy. "Mutations in the EMD gene can lead to either the loss or dysfunction of Emerin, with particularly notable implications for the development of Emery-Dreifuss muscular dystrophy (EDMD), a disorder marked by defects in cardiac and skeletal muscle function." (PMID 40433544, 2025). "We also identified Lmo7 (LIM domain only 7) in the heart proteome; Lmo7, a signaling transcription factor genetically linked to Emery-Dreifuss muscular dystrophy, binds emerin but to our knowledge is untested for binding to lamin A." (PMID 37936983, 2023). "For example, mutations in the gene encoding the ubiquitously expressed NEP emerin cause a severe disease called Emery-Dreifuss muscular dystrophy (EDMD), which is characterized by skeletal muscle wasting and cardiac pathology." (PMID 36377660, 2022). "For instance, Emerin overexpression increased nuclear size, in agreement with the altered nuclear size reported in patients with Emery-Dreifuss muscular dystrophy caused by mutations in emerin." (PMID 36299481, 2022). "Of these, emerin is the most studied in the context of skeletal muscle biology, due to mutations in emerin giving rise to Emery Dreifuss muscular dystrophy." (PMID 34368139, 2021). "Emerin (EMD) encodes a serine-rich nuclear membrane protein which located on the cytoplasmic surface of the inner nuclear membrane and related to X-linked Emery-Dreifuss muscular dystrophy (EDMD)." (PMID 32226785, 2020). "This is further supported by mutations in the intrinsically disordered domain of emerin, which have been shown to cause Emery-Dreifuss muscular dystrophy 172–74." (PMID 32366843, 2020). "It is important to point out that Emery-Dreifuss muscular dystrophy is predominantly due to emerin gene mutations; moreover, cells derived from emerin knockout transgenic mice show mechanotransduction impairments." (PMID 30906328, 2019). "Mutations in the gene coding for emerin are associated with X-linked Emery-Dreifuss muscular dystrophy (X-EDMD)." (PMID 31185657, 2019). "For example, Emery-Dreifuss muscular dystrophy, which affects the skeletal and cardiac muscle, is commonly caused by mutation in the emerin (EMD) gene and less frequently by mutation in LMNA, and has also been associated with a mutation in the nesprin gene." (PMID 28134781, 2017). "Mutations in EMD in humans cause Emery-Dreifuss muscular dystrophy, characterized by skeletal muscle wasting and cardiomyopathy, and an autosomal dominant form is linked to mutations in LMNA." (PMID 28088180, 2017). "We have investigated Samp1 (Spindle Associated Membrane Protein 1), a transmembrane nuclear envelope protein, which interacts with emerin and lamin A, both of which are linked to Emery-Dreifuss muscular dystrophy (EDMD)." (PMID 29192166, 2017). "Mutations in the gene encoding emerin cause X-linked Emery-Dreifuss muscular dystrophy (EDMD), an inherited disorder causing progressive skeletal muscle wasting, irregular heart rhythms, and contractures of major tendons." (PMID 29065506, 2017). "A role of Asna1/TRC40 in INM biogenesis is also provided by data on Emerin, a TA protein associated with Emery-Dreifuss muscular dystrophy." (PMID 27765046, 2016). "Emery-Dreifuss muscular dystrophy (EDMD) was initially linked to mutations in the EMD gene, which encodes the INM protein emerin, but can also be caused by mutations in LMNA and NE genes SYNE1, SYNE2 and TMEM43." (PMID 24490688, 2014). "One of these (HsInv0389) inverts the FLNA and EMD genes and has been associated to a deletion causing Emery-Dreifuss muscular dystrophy." (PMID 24651690, 2014). "A well-known example is Emery-Dreifuss muscular dystrophy, which is caused by mutations in the human lamin A/C and emerin genes." (PMID 24490688, 2014).
Emery-Dreifuss muscular dystrophy (continued). "Mutations in these proteins have been described in Emery-Dreifuss muscular dystrophy and attributed to disruptions of interactions at the NE with nesprins binding partners, lamin A/C and emerin." (PMID 23671687, 2013). "Loss of function mutations in the nuclear inner membrane protein, emerin, cause X-linked Emery-Dreifuss muscular dystrophy (X-EDMD)." (PMID 24010014, 2013). "For example, Emerin deficiency causes Emery-Dreifuss Muscular Dystrophy (EDMD) and MAN1 deficiency leads to osteopoikilosis, Buschke-Ollendorf syndrome and melorheostosis." (PMID 22745766, 2012). "The nuclear envelope proteins lamin A/C and emerin, mutations in which underlie Emery-Dreifuss muscular dystrophy, were also expressed in both quiescent and proliferating satellite cells." (PMID 19370151, 2009). "These include emerin, which is linked to Emery-Dreifuss muscular dystrophy, LBR, which is associated with Pelger Huet Anomaly and Greenberg skeletal dysplasia, and MAN1, which is linked to osteopoikilosis and melorheostosis." (PMID 17062158, 2006). "X-linked Emery-Dreifuss muscular dystrophy is caused by loss of emerin, a LEM-domain protein of the nuclear inner membrane." (PMID 15328537, 2004). "Importantly, recent work showed that siRNA-mediated knockdown of emerin encoding gene emd—ultimately causing X-linked Emery-Dreifuss muscular dystrophy (X-EDMD)—was associated with nuclear Ca2+ dysregulation in neonatal rat ventricular cardiomyocytes." (PMID 36979939, 2023). "X-Linked Emery-Dreifuss muscular dystrophy is caused by mutations in the gene encoding emerin." (PMID 36274837, 2022). "LMO7 directly interacts with the nuclear membrane protein Emerin and may be associated with Emery Dreifuss muscular dystrophy (EDMD)." (PMID 34576220, 2021). "Highlighting the importance of nuclear envelope proteins, mutations in genes encoding several of these proteins are associated with human diseases including Emerin (Emery-Dreifuss Muscular Dystrophy), Lamin A/C (Hutchinson-Gilford progeria syndrome) and Banf1 (Nestor-Guillermo progeria syndrome)." (PMID 34820387, 2021). "To test this, we analyzed RNA-Seq datasets, finding novel isoforms or isoform tissue-specificity for: Lap2, linked to cardiomyopathy; Nesprin 2, linked to Emery-Dreifuss muscular dystrophy and Lmo7, that regulates the Emery-Dreifuss muscular dystrophy linked emerin gene." (PMID 29912636, 2018). "Given its role in regulating emerin, this splice variant may be highly relevant for the study of Emery-Dreifuss muscular dystrophy (EDMD)." (PMID 29912636, 2018). "EMD codes for emerin, which is affected by mutations in X-linked Emery-Dreifuss muscular dystrophy." (PMID 28423600, 2017). "Emery-Dreifuss Muscular Dystrophy (EDMD) is genetically heterogeneous since it may be caused by a mutation in the STA gene encoding emerin (X-linked inheritance) or as AD trait determined by mutations in the LMNA gene encoding lamin A/C." (PMID 24065927, 2013). "Diseases with the same clinical symptoms can be caused by mutations in either lamins or in INM proteins (e.g. mutations in either lamins A/C or emerin can cause Emery-Dreifuss muscular dystrophy), emphasizing that some of these proteins have closely linked functions." (PMID 17062158, 2006). "Mutations in the EMD gene encoding emerin are associated with Emery-Dreifuss muscular dystrophy (EDMD), a degenerative disorder characterized by skeletal muscle wasting and cardiac abnormalities." (PMID 41596589, 2026). "Mutations in the gene encoding emerin are responsible for the majority of cases of X-linked Emery-Dreifuss muscular dystrophy (X-EDMD)." (PMID 31185657, 2019). "Mutations in the gene encoding emerin cause Emery-Dreifuss muscular dystrophy (EDMD), a disorder causing progressive skeletal muscle wasting, irregular heart rhythms and contractures of major tendons." (PMID 29065506, 2017).
Emery-Dreifuss muscular dystrophy (continued). "One nuclear membrane protein, emerin, is encoded by EMD, and an EMD mutation causes Emery-Dreifuss muscular dystrophy (EDMD)." (PMID 28290476, 2017). "Discovered in 1994, the EMD gene that codes for emerin, was the first molecular etiology for X-linked Emery-Dreifuss Muscular Dystrophy (EDMD)." (PMID 28854936, 2017). "For example, mutations in the gene for emerin (EMD) cause Emery-Dreifuss muscular dystrophy (EDMD), and mutations in the LEMD3 gene encoding MAN1 cause sclerosing bone dysplasias." (PMID 25790465, 2015). "The EMD gene, consisting of 6 exons and encoding a nuclear envelope protein emerin (254 amino acids), was involved in X-linked Emery-Dreifuss muscular dystrophy (EDMD)." (PMID 24997722, 2014). "Variants in the emerin gene (EMD) were implicated in X-linked recessive Emery-Dreifuss muscular dystrophy (EDMD), characterized by early-onset contractures of tendons, progressive muscular weakness and cardiomyopathy." (PMID 24997722, 2014). "Mutations in emerin cause X-linked Emery-Dreifuss muscular dystrophy (EDMD), a disease characterized by skeletal muscle wasting and dilated cardiomyopathy." (PMID 22606356, 2012). "Mutations in emerin cause X-linked Emery-Dreifuss Muscular Dystrophy (EDMD), a disease characterized by skeletal muscle wasting and irregular heart rhythms." (PMID 22606356, 2012). "For example, dystrophin is associated with the cytoskeleton and its absence causes Duchenne muscular dystrophy (DMD), while emerin is located in the nuclear membrane and its deficiency underlies X-linked Emery-Dreifuss muscular dystrophy (X-EDMD)." (PMID 21364987, 2011). "X-linked Emery-Dreifuss muscular dystrophy (X-EDMD; EDMD1) is caused by mutations in the gene encoding emerin." (PMID 36274837, 2022). "Loss-of-function mutations to EMD cause Emery-Dreifuss muscular dystrophy (EDMD)." (PMID 31599721, 2019). "Mutations in emerin also induce Emery-Dreifuss muscular dystrophy (EDMD)." (PMID 30261154, 2019). "Mutations in LMNA, EMD and BANF1 are genetically linked to many tissue-specific disorders including Emery-Dreifuss muscular dystrophy and cardiomyopathy (LMNA, EMD), lipodystrophy, insulin resistance and type 2 diabetes (LMNA) and progeria (LMNA, BANF1)." (PMID 31024910, 2019). "Lmo7 – Emerin is an INM protein, that binds both lamin A and the BAF complex and is frequently mutated in Emery-Dreifuss muscular dystrophy." (PMID 29912636, 2018). "Several studies on Emery-Dreifuss muscular dystrophy patients and model organisms support the role of emerin and LEMD2 in muscle integrity, but their potential role in neurons had not been explored." (PMID 24490688, 2014). "In addition, lamin A/C and emerin, which are expressed in quiescent satellite cells, are known as causal genes for autosomal-Emery-Dreifuss muscular dystrophy (A-EDMD) and X-EDMD, respectively." (PMID 24273513, 2013). "Bclaf, also named Btf, was identified in two separate yeast two-hybrid screens: one using E1B 19K, an anti-apoptotic protein from adenovirus and the second against Emerin, an integral nuclear membrane protein, involved in the Emery-Dreifuss muscular dystrophy." (PMID 17327826, 2007). "Emery-Dreifuss muscular dystrophy (EDMD) is inherited through mutations in either of two different genes: LMNA, encoding A-type lamins, and STA, which encodes a nuclear membrane protein named emerin." (PMID 15328537, 2004). "Loss of emerin leads to Emery-Dreifuss muscular dystrophy (EDMD)." (PMID 15328537, 2004). "This role is particularly clear from the aberrant nuclear shapes, lesions, and changes in gene transcription that are seen in cells with mutated or absent Emerin, as well as from its link to Emery-Dreifuss muscular dystrophy (EDMD) in humans." (PMID 38951951, 2024).
Emery-Dreifuss muscular dystrophy (continued). "While most emerin mutations lead to haploinsufficiency and a combined skeletal and cardiac muscle phenotype (X-EDMD, Emery Dreifuss muscular dystrophy), three mutations in the LEM domain of emerin were identified in patients presenting exclusively atrial cardiac defects." (PMID 36672271, 2023). "Loss of emerin, mutations in emerin-associated proteins (A-type lamins, nesprin-1, nesprin-2, LUMA) or mutations in transcription factor FHL1 are all genetically linked to Emery-Dreifuss muscular dystrophy (EDMD) (Meinke, Nguyen & Wehnert, 2011)." (PMID 24010014, 2013). "Since mutations in emerin cause Emery-Dreifuss muscular dystrophy and TMEM43 can affect emerin distribution, it has been suggested that TMEM43 mutations could result in muscular dystrophy." (PMID 22458570, 2012). "Mutations in NE proteins Emerin or Lamin A/C may cause Emery-Dreifuss muscular dystrophy (EDMD)." (PMID 19849840, 2009). "Specifically, mutations in both lamin A (LMNA) and emerin (EMD) lead to Emery-Dreifuss muscular dystrophy (EDMD), utosomal dominant EDMD in LMNA mutations and X-linked EDMD in EMD mutations, both associated with cardiac arrythmia." (PMID 35784481, 2022). "An exemplar of laminopathy/envelopathy is Emery-Dreifuss muscular dystrophy (EDMD), which is autosomal dominant when caused by mutations in LMNA, whereas it is X-linked when caused by changes in the NL-associated protein, emerin." (PMID 20376364, 2010).
muscular dystrophy (25 papers, 2008 to 2025). Muscular dystrophy (MD) refers to a group of more than 30 genetic diseases characterized by progressive weakness and degeneration of the skeletal muscles that control movement. "This INM protein interacts with emerin, and the conditional deletion of LAP1 from mouse skeletal muscle causes muscular dystrophy, whereas more severe phenotypes were observed coupled with emerin deficiency (emerin and muscle-specific LAP1 double-mutant mice)." (PMID 31430335, 2019). "Mutations in Lamin A/C and Emerin are associated with muscular dystrophies, suggestive of cell type specific co-regulation in Lamin A/C and Emerin function." (PMID 31117946, 2019). "Autosomal dominant missense mutations of lamin A/C cause a muscular dystrophy similar in phenotype to X-linked recessive deficiency of the emerin protein." (PMID 29750601, 2018). "While emerin-null mice exhibit only minor phenotypic changes, such as delayed skeletal muscle regeneration and repair, mild atrioventricular alterations, and motor coordination defects, humans with emerin deficiency develop muscular dystrophy." (PMID 40004006, 2025). "Our recent research has provided evidence that emerin deficiency contributes to the worsening of muscular dystrophy in H222P mice from adolescence, whereas cardiac dysfunction is not prominent in both H222P and Emd−/−/LmnaH222P/H222P double-mutant (EH) mice at 12 weeks of age." (PMID 37940872, 2023). "According to guidelines, in patients with muscular dystrophy associated with EMD mutations, early implantation of the PM may be justified, while in laminopathy, primary prevention of SCD should be realized by ICD implantation." (PMID 33673224, 2021). "We find evidence that a muscular dystrophy-linked EMD variant (EMDΔ95–99) is more rapidly degraded under acute stress conditions, suggesting that an overzealous response to ER stress could contribute to the pathogenesis of EDMD." (PMID 31599721, 2019). "However, many of these alterations bear striking resemblance to those seen in primary diseases of the nuclear envelope, for instance those caused by mutations in genes encoding, e.g., lamins, nesprins, or emerin, which frequently present with muscular dystrophy." (PMID 31218456, 2019). "To date, these findings have been limited to a few muscular dystrophy and lipodystrophy LMNA mutations but seem shared with a distinct nuclear envelope disease, emerin-deficient muscular dystrophy." (PMID 29750601, 2018). "It is noteworthy that elevated levels of MAP kinases and AKT/mTORC have been reported in emerin and lamin A mouse models for cardiomyopathy and muscular dystrophy." (PMID 25790465, 2015). "Notably, mutations in the genes encoding emerin and LAP1 also cause EDMD respectively a very similar muscular dystrophy." (PMID 36699009, 2022). "These proteins, together with Lamin A/C, Emerin, and Nesprins, among others, constitute the LINC complex, a molecular link that connects the nucleus to the cyto-skeleton, and have been associated with muscular dystrophies." (PMID 32455813, 2020). "Among muscular dystrophies, EDMD1 is linked to emerin mutations (EMD gene), EDMD2 and limb -girdle muscular dystrophy type 1B are caused by dominant lamin A/C mutations (LMNA gene), other forms of EDMD are caused by nesprin (SYNE1 and SYNE2 genes), FHL1, SUN1, or SUN2 mutations." (PMID 30781376, 2019).